PGK1 (phosphoglycerate kinase 1)
Diseases named in the same sentence as PGK1 in open-access papers (continued):
Sharing a sentence is not in itself a finding about the gene and the disease.
cancer (continued). "Several genes (B2M, EIF2B1, ELF1 and PSMC4; type 1 EC, and YWAZ, UBC, and PGK1; type 2 EC) were not identified in the combinations of five best genes for the two cancer sub-types (this study) suggesting that the transcriptome of these two EC sub-types may in fact be very different." (PMID 32439920, 2020). "Genes like PGK1, PFKP, HK2, and LDHA, that are involved in metabolic reprogramming of cancer cells by enhancing glycolysis have a negative correlation with PEBP1/STK11 co-expression." (PMID 40806276, 2025).
infection (16 papers, 2009 to 2026). The state of being infected such as from the introduction of a foreign agent such as serum, vaccine, antigenic substance or organism. "The increased gluconeogenesis during LCMV infection resembled that seen during starvation or cachexia, however the infection also up-regulated mRNA encoding glycolytic enzymes (PGK1, GCK, GAPDH and ALDOB) that are usually down-regulated during a fast." (PMID 19216742, 2009). "This indicates that BoHV-1 productive infection enhances the accumulation of PGK1 protein in mitochondria at later stages." (PMID 40055833, 2025). "As previously reported, PGK1 mRNA levels also significantly decreased 24 h after infection, which aligns with the reduction in protein levels." (PMID 40055833, 2025). "Specifically, compared to the control, PGK1 protein levels declined to approximately 68.48% and 55.10% after infection for 36 h and 48 h, respectively." (PMID 40055833, 2025). "In contrast, HIF-1α-specific target genes including Nos2, Pgk1 and Ldha are dramatically increased upon infection, and these are predominantly expressed in monocyte-derived macrophages." (PMID 40191198, 2025). "Western blot analysis verified three selected proteins involved in glycometabolism pathways, namely PGM1, PKM, and PGK1 were increase over time post the infection." (PMID 35869254, 2022). "While DMOG increased both HIF-1α-specific targets Nos2 and Pgk1 in LysMCreARNTf/+ macrophages compared to untreated cells during infection, this effect was only significant for Nos2 expression." (PMID 34959539, 2021). "With this in mind, we explored whether BoHV-1 productive infection coordinates the PGK1 signalling pathway to facilitate viral replication cycles." (PMID 40055833, 2025). "Additionally, it has been noted that BoHV-1 productive infection disrupts Nrf2 signalling, exacerbates oxidative stress, and increases the accumulation of PGK1 in mitochondria." (PMID 40055833, 2025). "Additionally, BoHV-1 productive infection increases the accumulation of PGK1 proteins in the mitochondria." (PMID 40055833, 2025). "Thus, the knockdown of PGK1 expression using siRNA decreases viral productive infection, indicating that PGK1 signalling is required for the efficient replication of BoHV-1 in MDBK cells." (PMID 40055833, 2025). "However, BoHV-1 productive infection reversed the effects that PGK1 signalling had on β-catenin expression, as shown in mock-infected cells." (PMID 40055833, 2025). "Our study discovered that PGK1 is crucial for productive infection by BoHV-1." (PMID 40055833, 2025). "Both viruses utilise PGK1 signalling for efficient infection." (PMID 40055833, 2025). "To investigate the role of PGK1 signalling during in vitro infection, we first examined whether BoHV-1 infection affects PGK1 protein expression in MDBK cells." (PMID 40055833, 2025). "The positive correlation with CXCL1, CXCL16, and CCR1 indicated that PGK1 may contribute to the recruitment of immune cells, such as macrophages and T cells, to the site of infection or inflammation." (PMID 39712033, 2024). "Notably, G6PD, ACLY, and PGK1 were also detected in our IP-MS analysis of SIRT2 interactions during infection." (PMID 37916830, 2023). "In addition, many metabolic enzymes such as glucose-6-phosphate isomerase and phosphoglycerate kinase 1 are also modified by ISG15 following infection with Listeria either at dimerization domains or at active sites of the enzyme." (PMID 31772204, 2019). "We observed lower levels of PGK1 protein in MDBK cells infected with BoHV-1 at 12 and 24 h after infection." (PMID 40055833, 2025). "After the PGK1 protein was knocked down, the mRNA levels of bICP27 and VP16 were reduced to approximately 77.67% and 17.8%, respectively, 24 h after infection." (PMID 40055833, 2025). "We found several reference genes were differentially expressed in infection control mice (i.e., IPO8, PGK1 and ALAS1) in response to sporozoite challenge." (PMID 38030676, 2023).
infection (continued). "Consistently, under hypoxia, the infection of the wild-type EPEC E2348/69 strain induced the expressions of PDK1, PGK1, SLC2A1 (GLUT1), and PKM2, four well-defined HIF-1α targets, but did not induce the expression of SOD2, a well-defined HIF-2α target." (PMID 30125331, 2018). "SVA infection in mice increased expression of PKM and PGK1 in tissues and serum yields of lactate." (PMID 37126525, 2023). "The elevated expression of PGM1, PKM, and PGK1 accelerate the glycolysis pathway; thus, we speculated that the B. pseudomallei HNBP001 infection accelerated glucose uptake in host cells." (PMID 35869254, 2022).
myopathy (9 papers, 2012 to 2024). A disease of the muscle in which the muscle fibers do not function properly. "PGK-1 deficiency causes X-linked recessive hereditary chronic hemolytic anemia, myopathy, and neurological disorders due to insufficient ATP regeneration." (PMID 28649613, 2017). "Deficiency of the MYC target gene, phosphoglycerate kinase 1 (PGK1), from genetic mutations, may cause myopathy." (PMID 39457090, 2024).
neurodegenerative disease (8 papers, 2022 to 2025). A disorder of the central nervous system characterized by gradual and progressive loss of neural tissue and neurologic function. "Thus, it is reasonable to think that Pgk1 deficiency would be closely related to neurodegenerative diseases, owing to defective metabolic energy production." (PMID 35456967, 2022). "Our study significantly strengthens the case that PGK1 biology is of direct therapeutic interest for PD and neurodegenerative diseases in general." (PMID 39167658, 2024). "It has long been shown that both enhanced PGK1 activity and increased glycolysis alleviate neurodegeneration, and that energy deficiency may be a pathogenic factor in the pathogenesis of neurodegenerative diseases, leading to neuronal dysfunction and subsequent death." (PMID 35387336, 2022). "Studies have shown that PGK-1 plays a significant role in neurodegenerative diseases." (PMID 40746540, 2025). "However, it was recently discovered that low expression level of Pgk1 is related to many neurodegenerative diseases." (PMID 37582937, 2023). "Thus, dysregulation of Pgk1 and ATP6v1a represent a pathological loop linking energy deficits to lysosomal dysfunction, glial activation, and tau pathology, ultimately contributing to neurodegenerative disease progression." (PMID 40671812, 2025). "Therefore, we propose that extracellular administration of Pgk1 could serve as a neuroprotective drug that might be potentially applied in degenerative diseases." (PMID 37582937, 2023). "A recent preprint suggests that SARS-CoV-2 induces amyloid aggregation of several proteins involved in neurodegenerative diseases such as APLP1, ApoE, clusterin, α2-macroglobulin, PGK-1, ceruloplasmin, nucleolin, 14–3-3, transthyretin, and vitronectin." (PMID 36362302, 2022).
adenocarcinoma (3 papers, 2018 to 2021). A common cancer characterized by the presence of malignant glandular cells. "Strikingly, high expression of SLC2A1, encoding the glucose transporter GLUT1, and the glycolytic genes GAPDH and PGK1, were associated with strongly reduced OS, particularly in the adenocarcinoma subtype, consistent with the prognostic value of FDG-PET in LuAd." (PMID 31032816, 2019). "Surprisingly, we found that PGK1 was significantly increased in adenocarcinoma compared with other subtypes." (PMID 34091600, 2021).
metabolic disease (3 papers, 2012 to 2025). A congenital disorder (due to inherited enzyme abnormality) or acquired (due to failure of a metabolically important organ) disorder resulting from an abnormal metabolic process. "Given that PGK1 is the most significantly upregulated enzyme under HG stimulation and is known to play a pivotal role in metabolic disorders, we assessed its expression in placental chorionic villi tissues from NC and GDM patients." (PMID 40959277, 2025).
brain disorder (1 paper, 2015). A disease affecting the brain or part of the brain. "Therefore, future therapeutic intervention(s) to modulate PGK1 activity via HDAC3-mediated deacetylation may serve as a potential target for treating related diseases, such as hemolytic anemia and brain disorders associated with PGK1 dysregulation." (PMID 26356530, 2015).
gastrointestinal disease (1 paper, 2021). A disease that occurs in the gastrointestinal system, excluding the hepatobiliary system. "In the present study, we assessed the protective effect of terazosin targeting Pgk1 against gastrointestinal disease and evaluated the underlying mechanism in vivo and in vitro." (PMID 35008842, 2021). "The data above demonstrate that terazosin targets Pgk1 to activate glycolysis for treating gastrointestinal diseases." (PMID 35008842, 2021). "Our results indicate for the first time that terazosin significantly activates Pgk1-mediated protective defenses against gastrointestinal disease in an AKT- or Cas1/GSDMD-related pyroptosis manner." (PMID 35008842, 2021). "Our results demonstrated that terazosin protects gastrointestinal disease through activating Pgk1-mediated defense system." (PMID 35008842, 2021). "The study may provide a new protective agent by increasing glycolysis for gastrointestinal disease and address Pgk1 as an attractive candidate target to combat gastrointestinal disease." (PMID 35008842, 2021). "To investigate whether targeting Pgk1 display any effect on gastrointestinal diseases, we hypothesized that gain-function of Pgk1 influences the pressure resistance of intestinal epithelial cells." (PMID 35008842, 2021). "The study may provide a new protective agent by enhancing glycolysis for gastrointestinal disease and highlight Pgk1 as an attractive candidate target to combat gastrointestinal disease." (PMID 35008842, 2021). "Also, we find terazosin targets Pgk1 to benefit gastrointestinal disease by activating glycolysis, that may revolutionize the future therapy of the gastrointestinal diseases." (PMID 35008842, 2021).
PGK1 also shares sentences with these, for which no sentence is quoted: astrocytoma (5 papers); head and neck cancer (3); lymphoma (3); acute myeloid leukemia (2); benign tumor (2); COVID-19 (2); endometrial endometrioid adenocarcinoma (2); Hematological Disease (2); lobular breast carcinoma (2); neurological diseases (2); renal cell carcinoma (2); anaplastic meningioma (1); Arthritis (1); Autoimmunity (1); bacterial infections (1); bladder urothelial carcinoma (1); brain cancer (1); breast (1); breast disease (1); carcinosarcoma (1); cardiac arrest (1); cardiomyopathy (1); Cerebellar atrophy (1); cerebrovascular diseases (1); cholangiocarcinoma (1); Cornelia de Lange syndrome 4 (1); D-2-hydroxyglutaric aciduria (1); diabetic nephropathy (1); fatty acid metabolism disorders (1); follicular thyroid carcinoma (1).
A further 43 diseases each share a sentence with PGK1 in 1 paper.